AHR (aryl hydrocarbon receptor)
Diseases named in the same sentence as AHR in open-access papers (continued):
Sharing a sentence is not in itself a finding about the gene and the disease.
cancer (continued). "Remarkably, modulation of AhR activity by small molecules alters vital signaling pathways associated with cancer development and progression such as Wnt/β-catenin, PI3K/AKT, and mitogen-activated protein kinase (MAPK)/extracellular signal-regulated kinase (ERK) signaling pathways." (PMID 37241719, 2023). "Finally, higher expression of AhR in malignancies such as hepatic and lung cancers is likely associated with poor outcomes." (PMID 37241719, 2023). "However, AhR is overactivated in tumors, causing immune escape, and inhibiting the activity of AhR can activate the immune response; it is therefore a target in cancer immunotherapy." (PMID 37762693, 2023). "Such a finding may grant rational designs of new molecular targeting therapy for human cancers associated with environmental exposure to As3+ and other carcinogens, since AHR is highly targetable by either agonists or antagonists." (PMID 37151890, 2023). "Merging evidence suggested that AhR is a key sensor allowing immune cells to adapt to environmental alternations, and the activity has been proved to be associated with autoimmune disorders and cancer." (PMID 35831824, 2022). "Intriguingly, the constitutively active AhR gene (CA-AhR) expressed in transgenic mice also impaired the developmental processes of liver and kidney, disturbed neurogenesis, and increased the risk of cancers, e.g., in stomach." (PMID 35987825, 2022). "AhR silencing in this model was thus associated with cancer progression." (PMID 33451095, 2021). "Additionally, AHR activated by KYN can induce migration-associated gene expressions in cancer cells." (PMID 33422134, 2021). "In contrast, whether AhR signaling is directly associated with cancer cell proliferation remains unclear; nevertheless, it seems to affect proliferative capacity in some cancer cells." (PMID 33615198, 2021). "Additionally, in this study, two immunotherapeutic biomarkers (TMB and MSI) showed a significant association with AhR in some cancers." (PMID 34290693, 2021). "The relevant underlying pathways associated with AhR signaling in cancer were also explored." (PMID 34290693, 2021). "Besides IL24, other candidates AhR downstream genes both associated with cancer and migration were proposed to participate in the migration regulation of rutaecarpine by RNA-Seq and bioinformatic analysis." (PMID 34955744, 2021). "Thus, this research aimed to explore the underlying association between AhR and cancer immunotherapy in 33 human cancers." (PMID 34290693, 2021). "The inconsistency between results in these different studies may be due to the fact that some studies have compared the cancer cells with their AhR-deficient counterparts." (PMID 34848742, 2021). "In this regard, it is proposed to increase the level of kynurenic acid in brain tissues for therapeutic purposes, but the question arises whether activation of AhR by kynurenic acid will increase the risk of cancer." (PMID 32325928, 2020). "IPA of the 37 plasma-derived sEV protein features with ROC AUCs ≥ 0.70 revealed NKX3-1 (p = 1.4 × 10−9) as a top causal network, Cancer, Cell Death and Survival as a top disease function (p = 1.57 × 10−8) and AHR, VEGF, EGF, IRF1 and STAT3 as predicted significant upstream regulators." (PMID 32370304, 2020). "Beyond EMT, evaluation of AHR-regulated expression and activity patterns revealed several targets implicated in cancer progression, including members of the matrix metalloprotease family (MMPs, MMP9 and MMP24), asparagine synthetase (ASNS) and the ATF4 transcription factor." (PMID 33214553, 2020). "Emerging evidence suggests that AhR is a key sensor allowing immune cells to adapt to environmental conditions and changes in AhR activity have been associated with autoimmune disorders and cancer." (PMID 32435647, 2020). "Taken together, AhR could be considered as a candidate susceptibility gene for cancer based on its biological functional role." (PMID 33278884, 2020).
cancer (continued). "Accordingly, in the present study, meta-analysis with the most updated data was performed to explore whether AhR polymorphisms confer susceptibility to cancer." (PMID 33278884, 2020). "More investigations are required to evaluate the effect of AhR haplotypes on cancer susceptibility, which may supply the data basis for the meta-analysis of haplotypes." (PMID 33278884, 2020). "Therefore, some polymorphisms of AhR gene have been suggested as potential causal variants conferring susceptibility to cancer." (PMID 33278884, 2020). "Polymorphisms in AhR gene have been implicated in susceptibility to cancer." (PMID 33278884, 2020). "Cancer effect sizes (CES) were calculated for all AHR mutations in our BCa WES dataset." (PMID 32988402, 2020). "Moreover, epidemiological and experimental animal data provide evidence for an association between AhR and cancer initiation and progression." (PMID 31936153, 2020). "Induction of CYP1A1 and CYP1B1 by environmental xenobiotic chemicals or endogenous ligands through the activation of the aryl hydrocarbon receptor (AhR) has been implicated in a variety of cellular processes related to cancer, such as transformation and tumorigenesis." (PMID 31698770, 2019). "The induction of cytochrome P450 (CYP)1A1 and CYP1B1 by environmental xenobiotic chemicals or endogenous ligands through the activation of the aryl hydrocarbon receptor (AhR) has been implicated in a variety of cellular processes related to cancer, such as transformation and tumorigenesis." (PMID 31698770, 2019). "Thus, AhR is functionally linked with cancer stem-like properties, and it drives tumorigenesis in the occurrence of radioresistance." (PMID 29706625, 2018). "The underlying MoA of the AhR in cancers was reviewed in detail by Feng and colleagues." (PMID 29487603, 2018). "D’Amato and coworkers have recently demonstrated that Kynurenine substance generated by TNBC activates AhR causing the receptors to translocate to the cell’s nucleus to regulate the expression of target genes involved in cancer cell migration and immune system suppression." (PMID 28103884, 2017). "Our data show that the AhR is involved in the selective modulation of miRNA expression by cigarette smoke, and in particular suppressing levels of miR-96, a miRNA strongly implicated in cancer progression." (PMID 28079158, 2017). "Although AHR has been implicated in many human diseases and cancers, how AHR expression is maintained and regulated remains largely unknown." (PMID 28878246, 2017). "Modulation of AHR activity has been linked to various diseases, including numerous in vitro studies of breast, endometrial, kidney, lung and prostate cancers and inflammatory skin and bowel diseases." (PMID 28086803, 2017). "During recent years, the AhR has been also implicated in regulation of physiological functions of stem cells of various tissue origins, in particular in hematopoietic stem cells, or in cancer stem cells." (PMID 27274734, 2016). "Interestingly, the increased tumorigenicity of sh-AhR cells appeared to be associated to the accumulation of cancer stem-like cells." (PMID 26242870, 2015). "In addition, AhR activation has been associated with an increase in cyclooxygenase-2 and chronic inflammation leading to increased cancer risk." (PMID 25226618, 2014). "This concept seemed substantiated by studies on mice with high levels of active CYP1A1 (due to a high affinity AHR), which were more susceptible to cancers and genotoxicity when the PAH was brought in direct contact with the corresponding organs, but not after oral, systemic application." (PMID 22442665, 2012). "AhR-deficient cells show impairment in the Akt pathway, leading to the postulation that AhR antagonists could be useful as agents in cancer therapy." (PMID 22254019, 2010). "Indeed, AHR has recently been implicated in the regulation of ferroptosis in cancer more generally." (PMID 41540003, 2026).
cancer (continued). "However, the precise role of AHR in As3+-induced malignant transformation as well as cancer stem-like cell (CSC) formation, along with its underlying mechanisms, remains unclear." (PMID 40303305, 2025). "However, considering that a bioinformatics approach was adopted in this study, these findings are preliminary; thus, more studies on this topic need to be undertaken before the association between AhR and cancer immunotherapy is clearly understood and widely accepted." (PMID 34290693, 2021). "Future researches focusing on biological mechanisms and clinical phenotypes are required to clarify the exact role of AhR polymorphisms in cancer development, which may provide a sophisticated understanding of the link between AhR polymorphisms and cancer susceptibility." (PMID 33278884, 2020). "Notably, the AhR increases with age and is proposed to be a major driver of ageing and ageing-associated medical conditions, including most cancers, as well as increases in ageing-associated fatality risk to SARS-CoV-2 infection and other age-linked medical conditions." (PMID 33375613, 2020). "This example, among many others, demonstrates a complex role of the AhR in cancer progression and metastasis and shows that underlying mechanisms are still unclear and could depend on the nature of the ligand as well as on the cellular context such as the microenvironment." (PMID 33203443, 2020). "In addition, genetic differences in the properties of AhR are known to exist in human populations, and polymorphisms in cytochrome P450 enzymes have been associated with increased susceptibility to different cancers." (PMID 25257533, 2014). "Understanding the relationship between AhR signaling and circadian clock may provide a new insight into mechanisms underlying the development of a variety of disease states, including those associated with energy metabolism and cancer." (PMID 24987953, 2014). "We examine the involvement of AHR in pathologies such as cancer and autoimmune and inflammatory diseases and its potential as a therapeutic target." (PMID 41540003, 2026). "The involvement of AHR in cancer, which has long been suspected due to its connection with CYP1 enzymes in PAH metabolism, has emerged as more complex and multifaceted." (PMID 41540003, 2026). "Clinically, an AHR-ARNT loss-of-function signature correlated with reduced immune infiltration, poorer response to immunotherapy, and inferior survival across cancer types." (PMID 41721339, 2026). "Combined PARP7 inhibition and AHR activation leads to increased cancer cell death compared to the PARP7 inhibitor alone." (PMID 41326691, 2026). "As PARP7 can regulate AHR signaling, leading to altered expression of genes involved in immune response, we explored the interplay between PARP7 and AHR, in the context of cancer therapy." (PMID 41295982, 2026). "In this study, we provide compelling evidence that AHR suppresses transformation as well as the possible formation of cancer stem-like cells (CSCs) induced by low-dose As3+ exposure through the transcriptional repression of TOX." (PMID 40303305, 2025). "promotes cancer development via production of tryptophan and its metabolites, which act as a cancer-promoting aryl-hydrocarbon receptor (AhR) pathway activator." (PMID 40647535, 2025). "Together with the induction of the cell cycle arrest proteins p21 (CDKN1A) and p27 (CDKN1B), this underpins the pronounced decrease in cancer cell viability via the simultaneous AHR activation and PARP7 inhibition." (PMID 40493189, 2025). "Microbial metabolites, such as formate produced by F. nucleatum, have been shown to drive cancer cell invasion and metastatic spread by activating key signaling pathways, including the aryl hydrocarbon receptor, which enhances cancer stemness." (PMID 40181829, 2025). "AhR regulates cancer-related responses through both traditional genomic signaling and nongenomic pathways." (PMID 39578555, 2025).
cancer (continued). "N′-formylkynurenine is hydrolyzed to kynurenine (KYN), identified as a specific agonist of the human aryl hydrocarbon receptor (AHR), activation of which promotes invasiveness and accelerates growth of cancer cells." (PMID 40332338, 2025). "Disruption of this crosstalk through simultaneous PARP7 inhibition and AHR activation leads to extensive remodeling of the AHR-driven proteome and enhanced cancer cell growth suppression." (PMID 40493189, 2025). "L-Kyn appears to function as an oncometabolite as cancer cells exhibit increased Trp uptake and metabolism, resulting in elevated L-Kyn levels that activate the transcription factor aryl hydrocarbon receptor (AHR), promoting cancer cell growth." (PMID 40559444, 2025). "AhR activation is a critical pathway in many cancers, including HNSCC, which enhances cancer stem cell migration." (PMID 40647535, 2025). "AhR is a multifaceted regulator with diverse functions in detoxification, immune system modulation, tissue development, metabolism, and even cancer." (PMID 39940973, 2025). "This is relevant since inflammation-induced increases in IDO elevate KYN, acting as potent AhR agonists in the cancer microenvironment, promoting IDO expression in a feedback loop that suppresses innate immune responses by reducing NK cell function." (PMID 40115437, 2025). "The percentage of AHR-positive cases was significantly higher in normal lung tissue (10/10) compared to cancer tissue (47/135)." (PMID 40303305, 2025). "Flavonoids have emerged as significant modulators of the aryl hydrocarbon receptor (AhR), a transcription factor involved in processes like detoxification, immune regulation, and cancer." (PMID 39803270, 2025). "Key pathways include NF-κB, MAPK, PI3K/AKT/mTOR, and KP/AhR, which regulate cancer cell proliferation, angiogenesis, immunosuppression, and inflammatory responses." (PMID 40075568, 2025). "Flavonoids' dual roles as AhR modulators offer potential therapeutic benefits, particularly in cancer and immune‐related conditions, but their inconsistent effects call for further research." (PMID 39803270, 2025). "Our study further expands the current understanding of the interplay between microbial metabolites, AhR signaling, and ferroptosis in cancer." (PMID 40557796, 2025). "AHR agonist treatment has been shown to synergistic increase sensitivity to PARP7 inhibition in several different cancer cell lines, especially those insensitive RBN2397." (PMID 41432900, 2025). "The aryl hydrocarbon receptor (AHR) plays crucial roles in the control of stress, xenobiotic metabolism, inflammation, and cancer." (PMID 40765830, 2025). "The Kyn-AhR axis has been shown to enhance the malignant phenotype of cancer cells but suppress immune surveillance." (PMID 40759641, 2025). "Despite the increasing knowledge about AHR’s impact on protein-coding genes in cancer, its regulation of long non-coding RNAs (lncRNAs) in HCC remains largely unexplored." (PMID 40248203, 2025). "Increased ROS content is related to AhR and also takes part in cancer development and proliferation." (PMID 41301867, 2025). "BAY2416964 is an AHR antagonist reported to reduce cancer cell growth and is currently in clinical trials (NCT04999202)." (PMID 41432900, 2025). "In this study, we describe the synthesis and biological evaluation of new pyrazolopyrimidine derivatives as AhR antagonists for cancer immunotherapy." (PMID 41155994, 2025). "Inflammation induces changes in cellular metabolism, and AHR contributes to the metabolic alterations in cancer cells by regulating glycolysis and lipid metabolism through its interactions with various ligands." (PMID 40248203, 2025). "Nevertheless, the precise role of AHR in As3+-driven carcinogenesis remains uncertain, underscoring the need to elucidate the molecular mechanisms through which AHR modulates cancer initiation and progression." (PMID 40303305, 2025).
cancer (continued). "In parallel, KEGG pathway analysis further elucidated the involvement of the AHR target genes in various cancer-related pathways." (PMID 40248203, 2025). "One pathway connecting chronic inflammation to cancer development is via activation of the aryl hydrocarbon receptor (AHR), a transcription factor that can be stimulated by both endogenous and exogenous ligands produced during inflammatory processes." (PMID 40248203, 2025). "The involvement of the AHR and its associated genes in CRC was confirmed, demonstrating its likely role through E2F1 in this cancer." (PMID 41465541, 2025). "Kyn accumulation and its signaling through the aryl hydrocarbon receptor (AhR)—widely expressed in cancer cells and immune cells (T cells, macrophages, Tregs, DCs, MDSCs)—drives important immunosuppressive mechanisms." (PMID 41488637, 2025). "Compound 7k effectively modulated the AhR and AhR downstream genes, thereby down-regulation of PD-L1/PD-1 signaling in cancer cells and CD8 T cells." (PMID 41155994, 2025). "CRISPR-screens revealed that loss of AHR and PARP7 protect against the antiproliferative effects of RBN2397, while RBN2397 in combination with AHR activation synergistically increases sensitivity to RBN2397 across several cancer cell lines." (PMID 41432900, 2025). "The aryl hydrocarbon receptor (AHR) has recently emerged as a pivotal mediator of inflammation and immune regulation in cancers including PDAC." (PMID 41357201, 2025). "On the other hand, AHR activation can also have anti‐tumorigenic effects by promoting the differentiation and activation of immune cells that can target and eliminate cancer cells." (PMID 38868519, 2024). "Particularly, we observed that AhR was predominantly expressed in the nucleus in the five cancer types." (PMID 38680496, 2024). "Across human cancer types, IL4I1 gene expression associates more strongly with a pan-tissue AhR activation signature compared to that of either IDO1 or TDO, indicating IL4I1-generated metabolites as key AhR activators in cancer." (PMID 39211039, 2024). "Numerous phytochemicals found in nature and their synthetic equivalents can alter AhR signaling, making them promising candidates for use as chemopreventive or therapeutic agents against cancer." (PMID 39339278, 2024). "Investigating how the AhR expression pattern in NSCLC differs from that in other cancer types is crucial." (PMID 38680496, 2024). "Beyond its interaction with AR signaling, AHR has also been shown to engage with other cancer-relevant signaling pathways, including the Wnt/β-catenin, NF-κB, and MAPK pathways." (PMID 39600743, 2024). "BAY2416964 is a relatively new AHR antagonist and there are limited studies describing its ability to inhibit AHR and affect AHR dependent regulation of intrinsic cancer cell functions." (PMID 39450255, 2024). "Activation of the AhR is linked to metabolic disorders (e.g., AOP ID 57) and the progression of specific cancer types, which explains its presence in various cancer related AOPs (AOP IDs 416, 417, 420, and 439)." (PMID 38523647, 2024). "The involvement of AhR in this array of pathways sheds light on the multifaceted mechanisms through which AhR contributes to the development of cancer." (PMID 38518996, 2024). "The present study highlights the promising potential of hydroxy flavonoids as effective modulators of AHR, particularly in the context of cancer therapy, and reveals NAR as a potential AHR antagonist." (PMID 39204085, 2024). "In cell culture, HCB exposure has been shown to enhance cancer cell proliferation, migration, and invasion by activating AHR as a weak agonist." (PMID 38612627, 2024). "Recent research has expanded the understanding of AHR beyond xenobiotic metabolism, showing its involvement in critical cancer-related cellular processes like cell proliferation, differentiation, apoptosis, and immune modulation." (PMID 39600743, 2024).